TNF (tumor necrosis factor)
Diseases named in the same sentence as TNF in open-access papers (continued):
Sharing a sentence is not in itself a finding about the gene and the disease.
infection (continued). "A multiplexed bead assay was used to measure plasma levels of IL-5, IL-10, IL-12, IL-13, IFN-γ and TNF in BALB/c mice immunized against P. berghei K173 by repeated infection and drug cure before the first pregnancy." (PMID 24180253, 2013). "In our study secretion of TNF-α and IL-1β were also positively correlated with IL-6 in addition to IL-12, after 24 hours of infection." (PMID 23667550, 2013). "Mice were euthanized at 4 h, 24 h and 10 days after infection, and bacterial numbers, lung levels of inflammatory leukocytes, and lung expression of mRNA for inflammatory cytokines TNFα, IL-1β and mKC (IL-8 analogue) were evaluated." (PMID 23593362, 2013). "DCs induce production of numerous cytokines including TNFα, IL-6, IL-10, and IL-12 upon infection with Mtb in vitro." (PMID 24350246, 2013). "Tumor necrosis factor α (TNFα) is a pleiotropic pro-inflammatory cytokine that plays a pivotal role in the innate immune response to infection and tissue injury." (PMID 24086429, 2013). "TNFα is rapidly released after trauma, infection or exposure to endotoxin (lipopolysaccharide, LPS) and is one of the most abundant mediators of inflammation at local tissue level." (PMID 24236088, 2013). "Tumor necrosis factor alpha (TNFα) is a pro-inflammatory cytokine that is stimulated by NF-κB as a first line of defense against infection." (PMID 23630497, 2013). "Key cytokines for the protection during early phases of infection with Lm are TNF-α, IL-12 and IFN-γ." (PMID 23544144, 2013). "On days 6 and 9 post-infection, only mice infected with high doses of T. cruzi had a significant increase in the production of the proinflammatory cytokines TNF-α and IFN-γ." (PMID 23951243, 2013). "At 4 h post-infection, the lungs of Nlrc4−/−/Tlr5−/− had decreased levels of tumor necrosis factor (TNF) compared to WT control lungs." (PMID 23937571, 2013). "Cytokines such as TNF-α and IL-1β that are considered harmful to periodontal tissue in chronic inflammation play important roles in the control of pathogen infection in the acute inflammation." (PMID 23977160, 2013). "When cardiomyocytes were pre-incubated with IL-10 (20 ng/ml), Q-RT-PCR results showed a significant decrease in IL-6 and TNF-α mRNA levels after 4 h of infection." (PMID 24260222, 2013). "The production of tumor necrosis factor-α and interleukin-10 by MØ after infection with wild-type or mutant Mtb was examined using enzyme-linked immunosorbent assays." (PMID 23425360, 2013). "Three hrs after infection TNF-α was close to baseline in both genotypes, indicating that early innate immune response from resident corneal cells was not affected by lumican-deficiency." (PMID 23358433, 2013). "The investigators have also noted that Tumor Necrosis Factor-α (TNF-α), induced through infection by H. hepaticus, have been involved in the development of cancer in abdominal cavity, liver and other organs." (PMID 24475322, 2013). "The peripheral immune system normally produces various pro-inflammatory cytokines, including interleukin-1β (IL-1β), IL-6 and tumor necrosis factor-α (TNF-α) during infection." (PMID 24137231, 2013). "This study provides evidence that in severe S. aureus bacteremia in mice, TNF-α, IL-1α, and KC each can be useful as biomarkers predicting fatal outcome of infection." (PMID 23520553, 2013). "The pro-inflammatory cytokine TNF-α was comparably low 24 hours after infection, but significantly higher in the Lum−/− compared to Lum+/− infected corneas by 2–5 days after infection." (PMID 23358433, 2013). "We observed that stimulating macrophages with MRPs prior to infection induced NO and TNF-α production, as well as phosphorylation of MAPKs and nuclear translocation of transcription factors NF-κB and AP-1." (PMID 24086787, 2013). "The results indicated that, 24 h after infection, TNF-α production was significantly higher in cells infected with either RSV or RSV-PolyI:C than in cells treated with either hMPV alone or hMPV-PolyI:C." (PMID 24039959, 2013).
infection (continued). "Although T cell intrinsic TNF is dispensable for initial expansion of CD8 T cells up to day 9 post infection, intrinsic TNF/TNFR2 interactions potentiate contraction of the CD8 T cell response in the lung between day 9 and 12 post infection." (PMID 23874808, 2013). "IL-12 concentration was reduced in the liver during infection, whereas TNF-α production increased significantly in both peritoneal exudate and liver cells compared to noninfected mice." (PMID 23762152, 2013). "On the contrary, cells treated with TNF-α and insulin together showed more than a 50 percent decrease in glucose uptake but infection with IGFBP-3 abolished the TNF-α effect and restored levels of glucose uptake." (PMID 23383064, 2013). "Enhanced numbers of IFN-γ+ and TNF-α+ expressing NK and NK T-cells were seen in VIPhyb-treated WT and VIP-KO mice, with peak numbers of IFN-γ+ NK cells and TNF-α+ NK cells seen 40 hours after mCMV infection, compared with PBS-treated WT mice." (PMID 23723978, 2013). "In ELISA, upregulation of RANTES production after infection with RSV was inhibited by 1 μg/ml COX1 and COX2 inhibitors and upregulation of TNFα production after infection with RSV was inhibited by the 1 μg/ml COX2 inhibitor." (PMID 24058438, 2013). "Activated NF-κB, also in chondrocytes, is known to be involved in the regulation of several genes, including by infection, adhesion, cell-cycle, apoptosis, survival and inflammatory processes, by activating IL-1β, TNF-α, IL-6, Cox-2 and MMPs." (PMID 24283517, 2013). "In the group with M. leprae infected macrophages co-cultured with PBMCs, the concentrations of IL-2, IL-1β and TNF-α peaked on day 1 after infection and then declined gradually." (PMID 23782413, 2013). "We used RT-qPCR to investigate the level of expression of three cytokines characteristic of acute inflammation, TNFα, IL1β and mKC, a mouse analogue of human IL-8, at 24 h post infection." (PMID 23593362, 2013). "In contrast, ku80 infection was characterized by higher and lower expressions of TNFα and IL10, respectively." (PMID 24244155, 2013). "The reductions in TNF-α and IL-6 by AF-08 were prominent early in the infection, suggesting that the beneficial effect of AF-08 was due to the suppression of inflammation early after infection." (PMID 24250719, 2013). "TNF−/− mice were pre-treated with either saline (control) or dexamethasone prior to infection with P. aeruginosa." (PMID 24350219, 2013). "Although IFN-γ, IL-10, and TNF-α responses remained intact in the MLN and spleen late during infection of CXCR3-deficient mice, a significant decrease in IL-12 production was observed in the MLN and spleen of Cxcr3−/− mice." (PMID 24130498, 2013). "Activated NK cells lyse target cells directly by exocytosis of cytotoxic granules; they also secrete cytokines such as IFN-γ and TNF-α that mediate their immune response to infection." (PMID 24204766, 2013). "Early TNFα production was reduced in Ifnar1−/− mice infected through the intestinal tract and this was more pronounced after i.p. infection." (PMID 23840314, 2013). "In fact, TNF-α and IL-6 have been shown to contribute to the leakiness of the BBB caused by the TLR-3 mediated infection of mice with WNV." (PMID 24236107, 2013). "To identify host genes that are targeted by Yersinia during the infection process, we performed an RNA interference (RNAi) screen based on recovery of host NF-κB-mediated gene activation in response to TNF-α stimulation upon Y. enterocolitica infection." (PMID 24206648, 2013). "An increased TNF-α production was seen in mice pretreated with propolis, whereas IL-12 was downregulated during the infection." (PMID 23762152, 2013). "Rage−/− mice had lower TNF-α and IL-6 levels at 24 hours of infection and lower KC concentrations at 24 and 48 hours when compared with Wt mice." (PMID 24342460, 2013).
infection (continued). "It is important to note that the cytokines such as IL-1β and TNF-α are primarily synthesized and released by glial cells that can be activated by trauma, infection or the presence of endogenous yet abnormal protein aggregates." (PMID 24205200, 2013). "As expected, the infection induced IL-1, IL-6, KC, TNF-α, IL-10, IL-12, and IFN-γ release at all time points compared with noninfected mice." (PMID 23818746, 2013). "And TNF-α, in most cases, frequently induced in the presence of infection, plays a crucial role in the pathogenesis of ischemic AKI." (PMID 23853656, 2013). "Remarkably, infection with Seui strain induced higher TNFα, CD80 and IL-10 expression than pN3 treated cells." (PMID 24070317, 2013). "In this study, a burst of IFN-γ, IL-6, and TNF-α was observed in lethal influenza virus-infected mice, especially on day 4 after infection." (PMID 24373231, 2013). "Expression of iNOS and TNFα mRNA was upregulated following infection compared with that in naïve or sham-operated mice for up to 24 h, and declined thereafter." (PMID 23300453, 2013). "Our results point to an increase that is dependent on the immune system and that was triggered by the infection, since, similar to TNF-α, increased IL-10 after treatment has significantly higher levels than those observed in the healthy group." (PMID 23824716, 2013). "TNF-alpha is produced in response to pathological conditions like inflammation and infection mainly by activated macrophages and T lymphocytes, but also by several cell types including natural killer (NK) cells, mast cells, and fibroblasts." (PMID 24453421, 2013). "TLR activation signals through the NF-κB pathway to up-regulate the transcription of proinflammatory cytokines, including IL-1β, TNFα, and IL-6, which are essential for the recruitment of leukocytes to the lung and clearance of the infection." (PMID 23577168, 2013). "In severe S. aureus bacteraemia in mice, TNF-α, IL-1α, and KC are biomarkers predicting fatal outcome of infection." (PMID 23520553, 2013). "Infection with viable S. oralis WT strain induced the production of an inflammatory cytokine, TNF-α." (PMID 23658745, 2013). "Both IFN-β and TNF-α genes were induced progressively at different times after infection in ECV and HBMEC cells." (PMID 24236107, 2013). "We propose that TNF from innate, macrophage/neutrophil source is sufficient to keep an infection by attenuated M. bovis BCG under control until adaptive response with TNF from T cell origin comes in play." (PMID 25400917, 2013). "We observed at 14 hours post infection a statistically significant 40-fold increase in levels of IL-6 and TNF alpha, and a 4-fold increase in IL-1 beta compared to the mock treated mice." (PMID 23874613, 2013). "Three hours after infection, when neutrophils have yet to infiltrate the cornea, TNF-α concentration was close to baseline in infected corneas of both genotypes." (PMID 23358433, 2013). "We found here that the infection of resting and INF-γ-activated MØ with wild-type Mtb or ΔkstD mutant caused the release of equal amounts of TNF-α." (PMID 23425360, 2013). "Caution should therefore be recommended when considering the immune modulation with administration of anti-TNF-α mAb in an active infection setting." (PMID 23527251, 2013). "IFNγ and TNFα production by PBMCs is of pivotal importance in generating an appropriate bactericidal response to infection." (PMID 23935244, 2013). "This was not unexpected, since prior studies with hamsters have shown TNF-α expression in the spleen is induced early at 3–10 days post-infection and then declines." (PMID 23533629, 2013). "This occurs when infected Mφs and chronic Mφs are killed through TNF-α induced apoptosis or T cell mediated killing at the initial stages of simulated infection." (PMID 23869227, 2013). "In accordance, our results suggested that after 24 h of infection, there is lower TNF-α and IFN-γ production in alveolar space of 5-LO−/− mice." (PMID 23991239, 2013).
infection (continued). "Experimental evidence has revealed that tumor necrosis factor (TNFα) plays a major role in host defense against Mtb in both the active and chronic phases of infection." (PMID 23308269, 2013). "Th17 cells exert their biological effects via the secretion of IL-17A, IL-17F, IL-6, IL-22 and TNF-α, which signals neutrophils to move towards the site of inflammation and play an infection-fighting role in the early stage of the immune response." (PMID 23403648, 2013). "IL8 promoter activity was increased 5-fold by TNF-α stimulation, and infection with P. gingivalis WT significantly reduced IL8 promoter activity to 3.6-fold over unstimulated basal levels." (PMID 23637609, 2013). "We have shown by in vitro experiments that primary Chlamydia infection of human epithelial cells and mouse macrophages occurs within 2 days of infection and is characterized by significant production of IL-6, TNF, and IL-8." (PMID 23766556, 2013). "For example, IL-1β, IL-6, and TNF-α can be regarded as pro-inflammatory cytokines due to their role in early host defence against infection or disease, and in the development and progression of inflammation." (PMID 24146637, 2013). "At 3 dpi, IL-4, IL-6 and TNF were upregulated similarly in response to both virus strains and remained upregulated throughout the course of infection." (PMID 23342177, 2013). "Conversely at 24 hours post infection, TNF levels were consistently enhanced in Nlrc4−/−/Tlr5−/− mice when compared to Nlrc4−/− or WT mice." (PMID 23937571, 2013). "By 24 hrs after infection the level of TNF-α had increased to similar extents in Lum+/− and Lum−/− corneas (94 and 84 pg/ml on average, respectively)." (PMID 23358433, 2013). "Further study will be needed to analyze the role of chicken TNF-α in the HPAIV infection since there are few papers dealing with TNF response in chickens on the infection with avian influenza virus." (PMID 23874602, 2013). "Small intestine inflammation also develops in mice in which TNF has been over-expressed, such as in TNFΔARE mice, and in certain mouse strains following infection with Toxoplasma gondii." (PMID 23451046, 2013). "TNF-α is a proinflammatory cytokine that plays a crucial role in the response to tissue injury, infection, and inflammation." (PMID 23516562, 2013). "In conclusion, we have identified two separate immune mediated mechanisms of hypophagia during infection induced gastrointestinal and peripheral inflammation, which act via the distinct pathways of I-cell hyperplasia and TNFα cachexia." (PMID 23349631, 2013). "These molecules enable TNFα-activated endothelial cells to attract, activate and recruit circulating leukocytes, which subsequently extravasate to reach the site of infection or injury." (PMID 24086429, 2013). "On the other hand, IL-2 and IL-4 levels in TNF-α KO mice were significantly higher than those of WT and IL-10 KO mice during mock infection and following JaOArS982 infections." (PMID 23940775, 2013). "Under certain circumstances, monocytes do differentiate into DCs during infection that produce inflammatory mediators such as TNF-α, nitric oxide (NO−) and reactive oxygen species, as in Listeria monocytogenes infection." (PMID 23690669, 2013). "The TNF-α expression level was slightly increased in spleens throughout the course of infection, whereas it was decreased in kidneys of H8912-infected mice except at day 6 post-infection." (PMID 23785537, 2013). "During complicated infection, overly expressed TNF-α and IL-10 thus act to downregulates IL-6 production." (PMID 24324686, 2013). "Excessive up regulation of TNF-α observed in complicated cases indicates host response to contain the infection and prevent tissue injury." (PMID 24324686, 2013). "Variations in renal and liver function tests and serum TNF-α and NOx levels in surviving cirrhotic rats between the infection of E.coli and the laparotomy." (PMID 23527251, 2013).
infection (continued). "Mediating the recruitment of additional immune cells to the site of infection remains their most important task and members include ligands of the interleukin-1 (IL-1) family such as IL-1β and tumor necrosis factor-α (TNF-α)." (PMID 23971044, 2013). "As determined by ELISA, TNF-α levels in media from HIV-infected PBMCs ranged from 300–400 pg/ml at 4 days post- infection, ∼100 pg/ml in uninfected PBMC media, and was undetectable in media from cell-free virus or control media." (PMID 23554879, 2013). "Statin-treatment in infected macrophages resulted in increased IL-12p40 and TNF-α and up to 4-fold reduced bacterial burden within 6 hours post infection, demonstrating a direct effect of statins on limiting bacterial growth in macrophages." (PMID 24086542, 2013). "A549 epithelial cells mainly produced the inflammatory cytokines IL-6 and TNF-α in an infection dependent process, while IL-8 was induced by live RSV and still in significant amounts by non-infectious virus." (PMID 24303065, 2013). "To further check how Fas and FasL influence the cytokine and chemokine production in vivo we assessed vaginal lavages for the production of chemokines (CXCL1, CXCL9 and CXCL10) and interleukins (IL-1β and TNF-α) at 3 and 7 day of infection." (PMID 23922974, 2013). "Specifically, an oscillation pattern was observed in the temporal response of NF-κB activation, a feature similar to that observed in reporter cell lines following stimulation with TNF-α, LPS and IL-1β or infection with Helicobacter pylori." (PMID 23383093, 2013). "Tumor necrosis factor alpha (TNF-α) plays an important role in inflammation, immunity, and defense against infection and clearance of human papillomavirus (HPV)." (PMID 23870134, 2013). "Downstream of TNFα, IL-1β, and IL-6 other cytokines are released such as IL-8 that induce migration of neutrophils and phagocytes to the site of infection." (PMID 24391635, 2013). "While TLR2 knockout (KO) mice were able to eradicate infection in a similar manner to control mice, they had reduced TNFα and CXCL2." (PMID 23457650, 2013). "H37Rv infection of neutrophils resulted in more than 28-fold increase in the production of TNF-α compared to uninfected neutrophils." (PMID 24312131, 2013). "We and others also have shown that there is an initial surge of TNF-α production in the GTs of infected mice during the first week of infection, and that the levels gradually reduce during the subsequent weeks of infection." (PMID 23483844, 2013). "Tissue at the site(s) of inflammation or infection release cytokines, including interleukin (IL)-1, IL-6, and tumor necrosis factor (TNF)-α." (PMID 26464911, 2013). "In contrast, the second hypophagic response is extra-intestinal and due to the anorectic effects of TNFα during peripheral infection of the muscle." (PMID 23349631, 2013). "In the course of bacterial CNS infection different proinflammatory proteins such as TNFα attract leukocytes to the site of infection." (PMID 23448224, 2013). "Triple-positive polyfunctional CD4+ T cells were evaluated in the spleen, and although Mtb induced increases in spleen CD4+IFN-γ+ and CD4+IL2+ cells, the infection significantly reduced the frequencies of triple-positive CD4+TNF-α+IFN-γ+ cells." (PMID 24250805, 2013). "Despite these studies, research into the increased rate of serious infections in RA patients since the introduction of anti-TNF therapy in the U.S. is still limited." (PMID 24498926, 2013). "In 5-LO−/− mice, levels of TNF-α were lower 24 h after infection and higher after 72 h compared with cytokine levels of WT-infected mice." (PMID 23991239, 2013). "The hallmark of the infection is a very strong immune response as indicated by high IFN-γ and TNF-α production, but very few parasites present within the lesions." (PMID 23555256, 2013). "Scutellariae radix (SR) and Gardeniae fructus (GF) showed abilities to reduce bacteria shedding and suppressing serum level of TNF-α induced by infection in swine." (PMID 23533497, 2013).